BECN1 (beclin 1)
Diseases named in the same sentence as BECN1 in open-access papers (continued):
Sharing a sentence is not in itself a finding about the gene and the disease.
tumor (continued). "BIRC2/cIAP1 and Beclin-1 expression were determined through immunohistochemistry, where brown staining in tumor cells signified positive staining, with varying intensities measured in the tissue sections." (PMID 38596136, 2024). "CUL3 mediated the K48-linked ubiquitination of beclin 1 (BECN1), leading to its degradation and subsequent reduction in autophagy, ultimately contributing to tumor progression." (PMID 39678497, 2024). "Early indications of autophagy's capability to suppress tumor growth emerged from research focused on the beclin-1 (BECN1) gene." (PMID 38741166, 2024). "Consistent with our in vitro data, the main proteins involved in autophagosome formation, namely ATG12-ATG5 (ATG5) and Beclin 1, were upregulated in tumor tissue following single treatment with Abi." (PMID 39409882, 2024). "To further validate the induction of autophagy by BDS-hEA in tumor tissues, we conducted immunohistochemical analysis to assess the protein levels of p62, Beclin-1, and LC3-II." (PMID 39091624, 2024). "The present review will comprehensively investigate how Beclin-1 controls autophagy in human cancers, assessing its effects on tumor advancement and drug resistance." (PMID 39650649, 2024). "Beclin-1 has a dual role in BC development, both inhibiting tumor growth and promoting tumor survival." (PMID 39273650, 2024). "BECN1 was involved in the regulation of the occurrence and development of NB and had a similar effect in protecting and promoting the growth of tumor cells." (PMID 39411839, 2024). "A recent study reported that the long noncoding RNA FIRRE acts as a tumor promoter by interacting with PTBP1 to stabilize BECN1 mRNA and facilitate autophagy." (PMID 39156764, 2024). "Overall, the complex roles of Beclin-1 in the tumor immune microenvironment, immunotherapy, and drug sensitivity make it an important focus of cancer treatment research." (PMID 39650649, 2024). "In particular, a recent study demonstrated that CUL3 inhibits autophagy by ubiquitinating and degrading Beclin-1, thus promoting tumor progression." (PMID 36831455, 2023). "These established references suggest the potential of both ULK1/2 and Beclin-1 inhibitors to suppress the autophagic pathway and improve apoptosis in cells bearing tumor antigens." (PMID 37893079, 2023). "In contrast to Beclin-1, there is evidence of other autophagic proteins that have an effect on tumor progression." (PMID 37893079, 2023). "Examples of autosis have been reported in cultured cells after prolonged starvation or treatment by a Beclin 1-derived peptide (Tat-Beclin 1), in cardiomyocytes after ischemia/reperfusion injury and in tumor cells after CAR-T therapy." (PMID 36765914, 2023). "This study offered convincing evidence that autophagy can inhibit tumorigenesis and the autophagy-related gene Beclin 1 functions as a tumor suppressor gene." (PMID 38069199, 2023). "The E3 ubiquitin-protein ligase, CUL3, inhibits autophagy by mediating the ubiquitination and degradation of BECN1, thereby promoting tumor occurrence and development." (PMID 36611207, 2023). "NEDD4 also promotes ubiquitination and degradation of Beclin 1, a tumor-suppressive protein and a central autophagy mediator." (PMID 37176148, 2023). "Recent studies have found that the System Xc- inhibitor erastin induces ferroptosis in tumor cells followed by increased protein expression levels of BECN1, a key regulator of autophagy." (PMID 37733667, 2023). "At the protein level, APS increased the phosphorylation of AMPK and BECN1 in tumor tissues, and APS decreased the protein expression of GPX4 in tumor tissues." (PMID 37733667, 2023). "In both BECN1-high and BECN1-low tumors, the model focuses on tumor and mucus regions; however, in BECN1-high tumors, the model also focuses on regions occupied by lymphocytes, while in BECN1-low tumors the model focuses on the stroma." (PMID 37055393, 2023).
tumor (continued). "It has been shown that the F. nucleatum infection increased the motility of CRC cells and elevated the expression of CARD3, LC3-II, BECN1 and vimentin, and decreased the expression of E-cadherin and p62 in tumor cells." (PMID 36835075, 2023). "Apatinib can inhibit the VEGFR2/STAT3/Bcl-2 signaling pathway and increase the expression of beclin-1 in vivo, thereby inducing autophagy and apoptosis of tumor cells." (PMID 37124541, 2023). "This limits DNMT3B‐mediated methylation in the Beclin 1 promoter region and induces upregulation of Beclin 1, promoting tumor cell autophagy and TAM resistance." (PMID 37837401, 2023). "provided further evidence by demonstrating that mice with heterozygous deletion of the BECN1 gene exhibited a substantially higher incidence of spontaneous tumours compared to wild‐type mice." (PMID 37837401, 2023). "Another study on lncRNA neighbor of BRCA1 lncRNA 2 (NBR2) revealed its tumor-suppressive role in HCC by inhibiting Beclin-1-dependent autophagy pathway via JNK and ERK signaling cascades." (PMID 36899946, 2023). "The expression of autophagic genes Beclin 1 is decreased in the HCC tumor samples, comparing to the adjacent normal tissues." (PMID 38069199, 2023). "Beclin-1 is a protein involved in oncogenesis and neurodegenerative diseases, through the process of autophagy, whose reinforcement provides better tumor response to treatment and enhanced overall prognosis." (PMID 37761179, 2023). "BECN1 is regarded as a haploinsufficient tumor suppressor gene since its heterozygous deletion in transgenic mice favors the spontaneous development of tumors in different tissues." (PMID 37566004, 2023). "One representative example, Beclin-1/ATG6, is a crucial factor in autophagy initiation and functions as a tumor suppressor." (PMID 38067169, 2023). "We have proved that FBXW7 regulate tumor cell autophagy through the regulation of the protein levels of BECN1, Atg7, and LC3." (PMID 37249289, 2023). "The tumor-suppressing role of autophagy was initially identified in a study of the BECN1 gene, which is monoallelically deleted in dominant portions of human breast, ovarian, and prostate tumors." (PMID 36831455, 2023). "Another autophagy-related protein, UVRAG, that interacts with Beclin-1 to initiate autophagy, has also shown a tumor-suppressive role in CRC." (PMID 37108476, 2023). "Activation of autophagy by chemotherapeutic drugs leads to the release of Beclin 1 from the Beclin 1-Bcl-2 complex, thereby increasing both autophagic flux and anti-apoptotic effects in tumor cells." (PMID 35159028, 2022). "BECN1 was initially identified as both an essential autophagy protein and a haploinsufficient tumor suppressor." (PMID 35832792, 2022). "For example, a mouse model with BECN1 deletion had a higher percentage of spontaneous tumor formation compared with BECN1 wild-type mouse." (PMID 36230955, 2022). "In the same way, Beclin-1, a main upstream regulator of autophagic sequestration, was also elevated in tumor-bearing mice compared to controls." (PMID 35847939, 2022). "Luteolin is known to regulate the expression of Beclin 1, which is an important regulator of autophagy during the nucleation step that results in tumor suppression." (PMID 36482329, 2022). "Beclin-1 immunolabeling level was investigated as a prognostic and predictive markerin multiple human neoplasms, and its role as a prognostic marker appears to be dependent on the type ofcancer." (PMID 34521293, 2022). "Recently, Beclin-1 has attracted increasing attention for its antitumor effects, and it has been regarded as a tumor suppressor protein that plays a key role in the lysosomal degradation pathway of autophagy." (PMID 36104717, 2022). "Histopathological examination revealed lower levels of LC3-II, ATG5/12, and Beclin 1 expression and higher levels of p62 expression in the tumor tissue of mice treated with hsa-miR-30a-3p compared with those that were not." (PMID 35449123, 2022).
tumor (continued). "In this manner, EGFR suppresses Beclin 1, leading to increased chemoresistance and tumor progression." (PMID 35159071, 2022). "In summary, tan IIA inhibits the mTOR pathway through different mechanisms and increases the expression of autophagy-related proteins, such as LC3-II and Beclin 1, thereby inducing autophagy in tumor cells." (PMID 36172186, 2022). "The same has been ascertained in tumor animal models and cancer-cell lines where a downregulation of BECN1 manifests a marked reduction in autophagy followed by enhanced cell proliferation." (PMID 36482329, 2022). "As is well known, LC3 is an essential marker of the autophagy cells and the autophagy regulated by Beclin-1 played a vital role in tumor genesis in several cancer types." (PMID 34974811, 2022). "Beclin-1 plays a key role in autophagy, a process that is increasingly recognized tobe dysregulated in neoplasia." (PMID 34521293, 2022). "Tumor histology and immunostaining for beclin-1 and LC3, GRP78, and cleaved PARP were performed to examine autophagy, ER stress, and apoptosis levels, respectively." (PMID 35740624, 2022). "Beclin-1, an essential Bcl-2-interacting autophagy protein, is a negative regulator of tumor formation and mammalian cell growth." (PMID 35682714, 2022). "We also observed markedly elevated expression of muscle-specific ubiquitin ligases Atrogin-1 and Murf-1, as well as autophagy pathway proteins such as LC3B-II and Beclin-1 in tumor-bearing mice compared to the control." (PMID 35847939, 2022). "Here, we used CRISPR/Cas9 technology to engineer tumor cells with various deletions of the ATGs, which are most frequently hit by SCNAs: BECN1, MAP1LC3B/LC3, and ATG10." (PMID 35681458, 2022). "Evidence demonstrates that the tumor-suppressive effect is derived from some ATG-proteins such as Beclin-1, which shows anti-oncogenic properties." (PMID 36160153, 2022). "The downregulated expression of Beclin-1 increased the sensitivity of tumor cells to chemotherapeutics." (PMID 36338726, 2022). "Some studies treated Beclin 1 as a dose-dependent tumor suppressor gene and found that Beclin 1-/- mice had early embryonic death." (PMID 36147481, 2022). "Human Beclin 1 (BECN1) is a key autophagy regulator that acts as haploinsufficient tumor suppressor since its decreased expression correlates with tumorigenesis and poor prognosis in cancer patients." (PMID 36008963, 2022). "Murine studies have shown that the deletion of the prime regulator of autophagy, Beclin-1, goes along with an increased likelihood of spontaneous tumor growth." (PMID 35406408, 2022). "When the expression level of Beclin-1 was reduced, the autophagy activity of cells would also be inhibited, so that tumor cells become more aggressive." (PMID 35414025, 2022). "In this study, the increased autophagosomes and elevated mRNA and protein expression of LC3-II/LC3-I and Beclin-1 in HeLa cells indicated that RA-induced autophagy in HeLa cells, which was in accordance with the effect of RA on other tumor cells." (PMID 34974811, 2022). "Most notably, Beclin-1, which is a fundamental gene involved in the autophagy pathway, is also an important tumor suppressor." (PMID 35884904, 2022). "How does Tat-BECN1 affect tumor growth, by autosis, ferroptosis or T cell-mediated immune response ?" (PMID 36172279, 2022). "Depletion of BECN1 led to significantly reduced xenograft tumor growth, concomitant with elevated RB and markedly reduced Ki67." (PMID 36230664, 2022). "The function of beclin-1 is inhibited by B-cell CLL/lymphoma 2, and thus, it has been demonstrated that beclin-1 acts as a tumor suppressor." (PMID 35054896, 2022). "Overall, these studies highlight the importance of BECN1 as both tumor prognostic marker and potential molecular target for the therapeutic treatment of cancer." (PMID 36008963, 2022). "It is worth mentioning that Beclin-1 often appears as a tumor suppressor gene in the process of tumor development." (PMID 35719323, 2022).
tumor (continued). "Together, this data help explain the observed tumor-mediated cardiac dysfunction that is likely related to an upregulation in cardiac inflammation (MyD88) and autophagy (beclin-1) leading to metabolic perturbations and atrophy (p-FOXO1)." (PMID 36531941, 2022). "Accordingly, we observed low LC3 expression and reduced PAI-1 expression in response to MitoX treatment in Becn1-silenced tumor sections." (PMID 33809137, 2021). "On one hand, it was found that Beclin-1 expression was increased in gastric carcinomas whereas the other observed a decreased expression compared to adjacent non-tumour tissue." (PMID 33743781, 2021). "On the contrary, Beclin-1 is a haploinsufficient tumour suppressor, known to be downregulated in many cancer types." (PMID 34238932, 2021). "For example, the deletion of Beclin-1, a mammalian gene of yeast ATG6, can promote tumorigenesis and support autophagy to inhibit tumor development." (PMID 34566636, 2021). "Beclin-1 is a bridge between autophagy and apoptosis of tumor cell, and is also a key factor involved in the regulation of autophagosome formation, which is essential in the occurrence and development of tumors." (PMID 34696663, 2021). "In our study, we demonstrate a statistically significant correlation between the immunohistochemical signal of Beclin-1 (within the nucleus) and the infiltration of the neoplasm." (PMID 34769649, 2021). "In conclusion, the immunohistochemical evaluation of Beclin-1 revealed a statistically significant correlation between the intensity of the molecule’s expression and a greater degree of infiltration of the neoplasm." (PMID 34769649, 2021). "BECLIN1 (ATG6/BECN1) which is an essential gene in autophagy as well as a tumor suppressor has been found deleted in various cancers, resulting in damage to mitochondria, oxidative stress, and disease progression." (PMID 33922139, 2021). "BECN1 is the first identified mammalian autophagy gene, and it is a haploinsufficient tumor suppressor coding for the BECLIN1 protein." (PMID 33925189, 2021). "In this study, we found that treatment with taxifolin increased the expression of autophagy-related proteins including LC3B-II, Atg7, atg12, and Beclin-1 suggesting that the autophagic pathway was activated in our tumor model." (PMID 34462635, 2021). "There is evidence that autophagy performs a tumor suppressor through its regulatory Beclin-1 protein, which has an anti-tumor role." (PMID 33507706, 2021). "The expression of Beclin-1 and Bcl-2 was evaluated in both tumor tissues and adjacent tissues using IHC." (PMID 34257544, 2021). "In the tumor-bearing vehicle-treated group, we observed a significant increase in relative transcript levels of Sqstm1, Map1lc3b, and Becn1 compared to all tumor-free groups (p < 0.0001 for all comparisons)." (PMID 33718372, 2021). "Notwithstanding, one should also take account of the tumor suppression of the autophagy-independent functions of Beclin-1." (PMID 34445095, 2021). "The activation mechanism of autophagy in the tumor cells involves the upregulation of Atg5, Beclin-1, and LC3II and downregulation of p62 protein expression." (PMID 34675987, 2021). "Our results showed low Beclin 1 level, high p62 accumulation as well as low miR-449a level in the tumors compared with the adjacent non-tumor tissues, which is consistent with the results of miR-449a by real-time PCR." (PMID 34737955, 2021). "Of note, Beclin-1 expression was significantly decreased in the HCC tissues compared to the adjacent non-tumour tissues." (PMID 33743781, 2021). "The autophagy gene Beclin-1 acts as a tumor suppressor, and interference in its expression can lead to tumor development." (PMID 34201882, 2021). "From the data collected in the literature, it is clear that Beclin-1 is related to the onset of neoplasms in different districts." (PMID 34769649, 2021).
tumor (continued). "Several studies have reported that BECN1± mutant mice models are more prone to develop tumours as compared to BECN1+/+ wild type mice, particularly lymphoma, liver and cervical tumours." (PMID 33802014, 2021). "The following variables were evaluated: percentage of positive expression of Beclin-1 by tumour cells, signal intensity of tumour cells, total score." (PMID 34769649, 2021). "In 1999, a study from Beth Levine’s lab demonstrated the role of BECN1 as a tumor suppressive factor, first linking autophagy with cancer." (PMID 34829881, 2021). "Injection of in-miR-224-5p-exo into the models decreased the expression of miR-224-5p and Ki67, decreased the protein expression of LC3-II and Beclin-1 and increased the protein expression of p62 in the tumor tissues." (PMID 34095151, 2021). "c-FLIP and Beclin-1 are key factors in the two pathways and they are both intriguing targets in anti-tumour therapies." (PMID 34238932, 2021). "These patterns extensively differ from those regarding BECN1, where tumor onset was not limited to a given organ but involved several tissues and with worse prognosis." (PMID 34830777, 2021). "A promising strategy is to target the autophagy pathway by silencing Beclin1 (BECN1), leading to improved NK cell infiltration into the tumor because of increased levels of the chemokine CCL5." (PMID 34572949, 2021). "It is known that Beclin 1 is an essential autophagy protein and has been shown to play a role in tumor suppression." (PMID 34440098, 2021). "Beclin-1 also plays a crucial role in the induction of autophagy, and is an established tumor suppressor that inhibits the genesis and progression of tumors by promoting autophagy and apoptosis." (PMID 34917504, 2021). "Another study found that the level of LC3II and the LC3II/LC3I ratio, as well as Beclin-1, increased in the liver of C26 tumor-bearing animals." (PMID 34440525, 2021). "As an important tumor suppressor gene, the study of Beclin-1, which has been identified as a novel Bcl-2-interacting protein, is vital to understanding the role of autophagy in tumorigenesis." (PMID 34257544, 2021). "The first autophagy gene described to be involved in tumor formation is Beclin-1, for which a monoallelic depletion has been observed in various cancers (e.g., breast, ovarian, prostate, hepatocarcinoma, or lymphoma)." (PMID 34745965, 2021). "The fact that the heterozygous disruption of BECN1 results in an increased frequency of spontaneous malignancies and decreased autophagy indicates that autophagy functions as a tumor suppression mechanism." (PMID 34829881, 2021). "Beclin-1, the mammalian orthologue of yeast Atg6/Vps30, is a coiled coil protein that act as a tumor suppressor (Vega-Rubín-de-Celis, 2020)." (PMID 33906303, 2021). "SH3GLB1/BIF1, which joins the BECN1 complex through UVRAG, is also a tumor suppressor; loss of SH3GLB1 inhibits autophagy while promoting tumorigenesis." (PMID 34829881, 2021). "The autophagy-related proteins include LC3, Beclin 1, and p62; LC3 serves as a specific marker of autophagosome formation and Beclin 1 has been identified as an essential modifier of the autophagic process, which is also involved in tumor development." (PMID 33750398, 2021). "Beclin-1 was reported as a haploinsufficient tumor suppressor gene that participates in the early stage of autophagosome formation in contrast to LC-3, which is a marker for final autophagasome formation." (PMID 34490076, 2021). "Beclin 1 (BECN1) is a gene that activates autophagy and programmatically inhibits tumor proliferation." (PMID 34250091, 2021). "The positive scores of Beclin-1 and Parkin were significantly high in tumor tissues compared to other markers." (PMID 34490076, 2021). "The tumor suppressor concept of autophagy was originally derived from the finding that BECN1 was deleted at high rates in sporadic human breast cancers and ovarian cancers." (PMID 33459128, 2021).